ALG9 (ALG9 alpha-1,2-mannosyltransferase)
Description:
Mannosyltransferase that operates in the biosynthetic pathway of dolichol-linked oligosaccharides, the glycan precursors employed in protein asparagine (N)-glycosylation. The assembly of dolichol-linked oligosaccharides begins on the cytosolic side of the endoplasmic reticulum membrane and finishes in its lumen. The sequential addition of sugars to dolichol pyrophosphate produces dolichol-linked oligosaccharides containing fourteen sugars, including two GlcNAcs, nine mannoses and three glucoses. Once assembled, the oligosaccharide is transferred from the lipid to nascent proteins by oligosaccharyltransferases. In the lumen of the endoplasmic reticulum, catalyzes the addition of the seventh and ninth alpha-1,2-linked mannose residues to Man(6)GlcNAc(2)-PP-dolichol and Man(8)GlcNAc(2)-PP-dolichol respectively.
Synonyms: DIBD1; CDG1L; GIKANIS; LOH11CR1J
Tractability: Antibody: UniProt predicts a signal peptide or a membrane-spanning region. PROTAC: ubiquitination databases record sites on it; its protein half-life has been measured.
Gene: Protein-coding gene on chromosome 11 (111,782,195 to 111,872,405, reverse strand). Ensembl gene ENSG00000086848.
Subcellular location: Endoplasmic reticulum membrane
Subcellular location (Human Protein Atlas): Endoplasmic reticulum
Pathways (Reactome):
Disease: Defective ALG9 causes CDG-1l
Metabolism of proteins: Biosynthesis of the N-glycan precursor (dolichol lipid-linked oligosaccharide, LLO) and transfer to a nascent protein
Gene Ontology:
Molecular function: dol-P-Man:Man(6)GlcNAc(2)-PP-Dol alpha-1,2-mannosyltransferase activity; dol-P-Man:Man(8)GlcNAc(2)-PP-Dol alpha-1,2-mannosyltransferase activity; alpha-1,2-mannosyltransferase activity; glycosyltransferase activity
Biological process: dolichol-linked oligosaccharide biosynthetic process; protein N-linked glycosylation
Cellular component: membrane; endoplasmic reticulum membrane; lumenal side of endoplasmic reticulum membrane
Genetic constraint (gnomAD): Loss-of-function variants: 54 observed, 79.46 expected, observed/expected ratio (o/e) 0.68, 90% interval 0.55 to 0.85. The upper end of that interval is the gene's LOEUF score, 0.85, which puts it in group 3 of 6, group 1 being the genes least tolerant of losing a copy. Missense variants: 623 observed, 753.93 expected, observed/expected ratio (o/e) 0.83, 90% interval 0.77 to 0.88. Synonymous variants: 277 observed, 276.51 expected, observed/expected ratio (o/e) 1, 90% interval 0.91 to 1.11.
Gene-disease validity (ClinGen):
ClinGen rates the evidence that ALG9 causes each of these diseases.
ALG9-associated autosomal dominant polycystic kidney disease (autosomal dominant): Definitive. Any autosomal dominant polycystic kidney disease in which the cause of the disease is a mutation in the ALG9 gene.
Homologues: Orthologues: chimpanzee ALG9 (99% identical), macaque ALG9 (98% identical), pig ALG9 (95% identical), dog ALG9 (95% identical), guinea pig ALG9 (93% identical), rat Alg9 (93% identical), mouse Alg9 (91% identical), tropical clawed frog alg9 (73% identical), zebrafish alg9 (72% identical), Drosophila melanogaster Alg9 (42% identical), Caenorhabditis elegans algn-9 (38% identical). Paralogues in human: PIGB (17% identical), ALG12 (14% identical).
Diseases named in the same sentence as ALG9 in open-access papers:
ALG9 is named in the same sentence as 38 diseases in open-access papers, as found by Europe PMC text mining. Sharing a sentence is not in itself a finding about the gene and the disease. The quoted sentences say what the papers report.
polycystic kidneys (4 papers, 2017 to 2023). "The current reported individuals diagnosed with a heterozygous pathogenic variant in ALG9 developed polycystic kidneys and occasionally a polycystic liver as an extrarenal manifestation." (PMID 37761895, 2023). "Defects in the N-linked glycosylation genes ALG3, ALG8, and ALG9, as well as the O-linked glycosylation gene B3GALTL, variably result in polycystic kidneys, cleft lip or palate, polycystic ovaries, and abnormal development of the brain including the corpus callosum." (PMID 28344780, 2017). "The phenotype in the genetically unsolved polycystic kidney and liver patients we identified to carry ALG6 variants is relatively mild, in many cases liver predominant and asymptomatic, consistent with the phenotype described for patients carrying a heterozygous ALG8 or ALG9 pathogenic variant." (PMID 36807342, 2023).
Kidney Cyst (3 papers, 2020 to 2024). Abnormal fluid filled sac within the kidney, either acquired or congenital. "Furthermore, in ID87.1, a 31-year-old female with negative family history, presenting with preserved kidney function and bilateral kidney cysts, we detected a heterozygous ALG9 truncating variant (c.427C>T, p.Arg143*)." (PMID 32398770, 2020). "We performed whole exome sequencing in a female with autosomal dominant polycystic liver disease (ADPLD) without kidney cysts and established the presence of a heterozygous missense variant (c.677G>C p.(Gly226Ala)) in ALG9." (PMID 37761895, 2023). "In this study, we identified an ADPLD patient without kidney cysts with a heterozygous pathogenic variant in ALG9." (PMID 37761895, 2023). "However, the diagnosis of a heterozygous pathogenic variant in ALG9 in an ADPLD individual without kidney cysts indicates that pathogenic variants in this gene are not restricted to ADPKD development." (PMID 37761895, 2023). "In conclusion, pathogenic variants in ALG9 are also associated with ADPLD without kidney cysts." (PMID 37761895, 2023).
liver cysts (3 papers, 2023). "We then stained liver cyst tissue from our patient with the ALG9 c.677G>C p.(Gly226Ala) variant with anti-ALG9 antibodies." (PMID 37761895, 2023). "In addition to ALG8, ALG9 heterozygous variants have recently also been implicated in the etiology of kidney and liver cyst phenotypes." (PMID 36807342, 2023). "ALG9 expression was absent in cyst wall lining from ALG9- and PRKCSH-caused ADPLD patients but present in the liver cyst lining derived from an ADPKD patient with a PKD2 variant." (PMID 37761895, 2023). "The absence of ALG9 in the ADPKD patient’s cyst wall lining suggests that the progression of liver cyst growth in ADPLD patients is different than in ADPKD patients, and that this progression in ADPLD is due to a molecular mechanism that requires high levels of ALG9." (PMID 37761895, 2023). "Indeed, ALG5 is found in the ADPKD population without PLD, and ALG9 in individuals with ADPKD who also have liver cysts." (PMID 37628703, 2023). "Interestingly, while kidney or liver cysts have been described, among multi-organ involvement in fetuses or children with ALG9-CDG or infrequently in ALG8-CDG, cysts have not been described for ALG6-CDG." (PMID 36807342, 2023).
acute myeloid leukemia (2 papers, 2022 to 2023). Acute myeloid leukemia (AML) is a group of neoplasms arising from precursor cells committed to the myeloid cell-line differentiation. "A previous study indicated that ALG9 was regulated by lncRNA MEG3 and participated in the drug resistance mechanism in acute myeloid leukemia." (PMID 35782861, 2022).
cyst (2 papers, 2021 to 2023). A sac-like closed membranous structure that may be empty or contain fluid or amorphous material. "WES revealed a heterozygous germline variant in the cyst-associated gene ALG9 in our patient." (PMID 37761895, 2023). "This disruption could explain the presence of ALG9 in the epithelium that lined the cyst of both ADPLD patients." (PMID 37761895, 2023). "We found that ALG9 was present in the cyst wall lining of both ADPLD patients but absent from the cystic wall lining of the ADPKD patient with the PKD2 (c.2584del) variant." (PMID 37761895, 2023).
cystic kidney disease (2 papers, 2025). A congenital or acquired kidney disorder characterized by the presence of renal cysts. "About 30% of cystic kidney disease variants were found in patients aged > 75 years, including variants in 4 genes causing ADPKD-like disease spectrum (ALG5, ALG9, DNAJB11, and monoallelic IFT140)." (PMID 40677324, 2025).
developmental delay (2 papers, 2006 to 2025). "In humans, mutations in ALG9 are associated with congenital disorders of glycosylation, presenting with growth retardation, skeletal abnormalities, and developmental delay." (PMID 41514807, 2025). "Inborn ALG9 deficiency (congenital disorders of glycosylation type IL) is associated with progressive microcephaly, seizures, developmental delay, and hepatomegaly." (PMID 16859551, 2006).
atherosclerosis (1 paper, 2015). A disease characterized by the build-up of fatty material and calcium deposition in the arterial wall resulting in partial or complete occlusion of the arterial lumen. "For example, in the Chr 9 locus, examination of hepatic eQTL identified 4 candidates; Nnmt (p = 1.27×10−8), 2310030G06Rik (p = 5.42×10−7), Alg9 (p = 1.05×10−6), and 1110032A03Rik (p = 2.27×10−6), whose eQTL are regulated by a SNP in high LD (r2>0.5) with the associated SNP for atherosclerosis." (PMID 26694027, 2015).
autosomal dominant polycystic kidney disease (1 paper, 2023). Autosomal dominant form of polycystic kidney disease. "α-1,2-mannosyltransferase (ALG9) germline variants are linked to autosomal dominant polycystic kidney disease (ADPKD)." (PMID 37761895, 2023). "Heterozygous pathogenic variants in ALG9 have been detected in patients with autosomal dominant polycystic kidney disease (ADPKD)." (PMID 37761895, 2023).
bipolar affective disorder (1 paper, 2006). "It is unknown whether common variations of ALG9 predispose to bipolar affective disorder." (PMID 16859551, 2006).
breast carcinoma (1 paper, 2021). "Expression levels of ALG1, ALG2, ALG3, ALG8, ALG9, ALG12 and ALG13 were differentially upregulated in radioresistant breast cancer tissues compared with those in radiosensitive tissues, particularly ALG3 with the highest level (4.53-fold change)." (PMID 33931075, 2021).
ciliopathy (1 paper, 2023). A genetic disorder of the cellular cilia or the cilia anchoring structures, the basal bodies, or of ciliary function. "Variants in PKD1 and PKD2 comprised 85.3% of the positive findings in this group, and other ciliopathy-associated genes (ALG9, PRKCSH, OFD1) accounted for an additional 3%." (PMID 37794564, 2023).
Gillessen–Kaesbach–Nishimura syndrome (1 paper, 2023). "Autosomal recessive loss of function variants in ALG9 cause congenital disorder of glycosylation type IL (CDG-IL or ALG9-CDG (OMIM #608776), or Gillessen–Kaesbach–Nishimura syndrome (OMIM #263210))." (PMID 37761895, 2023).
liver disease (1 paper, 2021). "The authors classified CDG based on liver involvement into two main groups: one with predominant/isolated liver involvement (MPI-CDG, CCDC115-CDG, TMEM199-CDG, ATP6AP1-CDG) and the other associated with liver disease (PMM2-CDG, ALG1-CDG, ALG3-CDG, ALG8-CDG, ALG9-CDG, PGM1-CDG)." (PMID 34291020, 2021).
ovarian carcinoma (1 paper, 2022). A malignant neoplasm originating from the surface ovarian epithelium. "To gain insight into changes in mannosyltransferases (ALGs), which have been found (ALG1, ALG2, ALG3, ALG9, ALG11 and ALG12) in ovarian cancer, we queried publicly available transcriptomic data, including Gene Expression Omnibus (GEO, GSE18520) and The Cancer Genome Atlas (TCGA) datasets." (PMID 36231102, 2022).
Saul-Wilson syndrome (1 paper, 2023). "Some disorders have also been reclassified as CDG as the expansion of their pathophysiological mechanisms has included underlying glycosylation defects (e.g., Saul-Wilson syndrome [COG4], Cowden syndrome 7 [SEC23B], ALG5- and ALG9-CDG)." (PMID 37858231, 2023).
steatosis (1 paper, 2021). Increased lipid within the cytoplasm of cells. "Additionally, ALG9-mediated inhibition of the expression of fat synthesis-related genes, such as FAS and SREBP-1c, reduced lipid deposition, improved the degree of steatosis, and exhibited lipid-lowering effects." (PMID 34574082, 2021).
Stroke (1 paper, 2020). Sudden impairment of blood flow to a part of the brain due to occlusion or rupture of an artery to the brain. "Exosomes harvested from Mir133b (paired with C87436, alpha-1,2-mannosyltransferase Alg9 and sorting nexin Snx7) overexpressing mesenchymal stem cells may improve neural plasticity and functional recovery after stroke in the rat brain." (PMID 32093602, 2020).
cancer (3 papers, 2021 to 2025). A tumor composed of atypical neoplastic, often pleomorphic cells that invade other tissues. "ALG9 is a glycogene whose reduced expression has been described during the epithelial-to-mesenchymal transition, an essential process also involved in cancer progression." (PMID 34071989, 2021). "First, we showed that AC displays a glycogene signature characterized by 42 glycogenes, where some of them, such as ALG11, ALG9, and B3GALT5, can be relevant for cancer patients." (PMID 34540372, 2021).
tumor (3 papers, 2012 to 2023). "We identified a house-keeping gene ALG9 (alpha-1,2-mannosyltransferase) used to normalize gene expression from NET tumor and blood, in all samples." (PMID 29467960, 2018). "The expression level of target genes was normalized to internal 18S; the presence of other housekeeping genes ALG9 and GAPDH was examined but was not utilized in calculations because these two genes were not consistently detectable in the tumor samples." (PMID 22720672, 2012).
skeletal dysplasia (2 papers, 2021). Any Mendelian diseases that affects growth and development of the skeleton. "In some of them (ALG12-CDG, ALG3-CDG, ALG9-CDG, PGM3-CDG, SLC35D1-CDG), a severe prenatal-onset skeletal dysplasia was observed and associated with an early death." (PMID 34441372, 2021). "Contrary to PMM2-CDG, skeletal dysplasia was well characterized in other CDGs, including ALG12-CDG, ALG3-CDG, ALG9-CDG, ALG6-CDG, PGM3-CDG, CSGALNACT1-CDG, SLC35D1-CDG and TMEM165-CDG." (PMID 34441372, 2021). "Contrary to PMM2-CDG, all remaining CDG, including ALG12-CDG, ALG3-CDG, ALG9-CDG, ALG6-CDG, PGM3-CDG, CSGALNACT1-CDG, SLC35D1-CDG and TMEM-165, are characterized by well-defined skeletal dysplasia." (PMID 34441372, 2021). "There is a group of CDGs, including ALG12-CDG, ALG3-CDG, ALG9-CDG, ALG6-CDG, PGM3-CDG, CSGALNACT1-CDG, SLC35D1-CDG, and TMEM-165 with well-defined skeletal dysplasia." (PMID 34441372, 2021). "Some types of CDG, including ALG3-CDG, ALG6-CDG, ALG9-CDG, ALG12-CDG, PGM3-CDG, CSGALNACT1-CDG, SLC35D1-CDG, and TMEM-165, were reported with well-defined skeletal dysplasia." (PMID 34540767, 2021).
infection (1 paper, 2022). The state of being infected such as from the introduction of a foreign agent such as serum, vaccine, antigenic substance or organism. "The C. neoformansALG3, ALG9, and ALG12 deletion mutant strains, generating truncated core N-glycans, do not show defects in early stages of host cell interaction during infection, including attachment to lung epithelial cells, opsonic/nonopsonic phagocytosis, and phagosome maturation." (PMID 36409123, 2022).
neurodevelopmental disorder (1 paper, 2025). A behavioral and cognitive disorder with onset during the developmental period that involves impaired or aberrant development of intellectual, motor, or social functions. "For instance, variants in genes such as ALG8 or ALG9 often result in a complex neurodevelopmental disorder of glycosylation." (PMID 41255767, 2025).
ALG9 also shares sentences with these, for which no sentence is quoted: epilepsy (2 papers); autosomal dominant polycystic liver disease (1); bipolar I disorder (1); cardiovascular disease (1); congenital disorder of glycosylation (1); epileptic encephalopathies (1); fructose intolerance (1); galactosaemia (1); glioma (1); kidney disorder (1); kidney failure (1); microcephaly (1); polycystic ovaries (1); psychosis (1); schizophrenia (1).